CUEDC1 (CUE domain containing 1)
Tractability: Antibody: the Human Protein Atlas places it where antibodies can reach. PROTAC: ubiquitination databases record sites on it; its protein half-life has been measured.
Gene: Protein-coding gene on chromosome 17 (57,861,243 to 57,955,851, reverse strand). Ensembl gene ENSG00000180891.
Subcellular location (Human Protein Atlas): Basal body; Centrosome; Plasma membrane; Primary cilium; Cytokinetic bridge; Cytosol; Microtubules; Mitotic spindle; Primary cilium tip
Gene Ontology:
Molecular function: protein binding; ubiquitin binding
Genetic constraint (gnomAD): Loss-of-function variants: 30 observed, 42.42 expected, observed/expected ratio (o/e) 0.71, 90% interval 0.53 to 0.96. The upper end of that interval is the gene's LOEUF score, 0.96, which puts it in group 4 of 6, group 1 being the genes least tolerant of losing a copy. Missense variants: 486 observed, 528.79 expected, observed/expected ratio (o/e) 0.92, 90% interval 0.85 to 0.99. Synonymous variants: 223 observed, 215.56 expected, observed/expected ratio (o/e) 1.03, 90% interval 0.93 to 1.16.
Homologues: Orthologues: chimpanzee CUEDC1 (98% identical), macaque CUEDC1 (97% identical), pig CUEDC1 (89% identical), dog CUEDC1 (89% identical), rat Cuedc1 (88% identical), mouse Cuedc1 (87% identical), guinea pig CUEDC1 (85% identical), rabbit CUEDC1 (82% identical), tropical clawed frog cuedc1 (68% identical), zebrafish cuedc1b (66% identical), zebrafish cuedc1a (56% identical), Drosophila melanogaster CG12024 (29% identical), and 1 more.
Diseases named in the same sentence as CUEDC1 in open-access papers:
CUEDC1 is named in the same sentence as 16 diseases in open-access papers, as found by Europe PMC text mining. Sharing a sentence is not in itself a finding about the gene and the disease. The quoted sentences say what the papers report.
breast carcinoma (2 papers, 2020). "In breast cancer, CUEDC1 as a cancer-promoting gene was essential for the ERα-mediated stimulation of cancer cell proliferation." (PMID 33099540, 2020).
cervical cancer (2 papers, 2020 to 2022). A primary or metastatic malignant neoplasm involving the cervix. "Several of our high scoring differentially methylated genes (SBNO2 and CUEDC1) are associated with body mass index (BMI)/inflammation and cervical cancer." (PMID 35169479, 2022). "Our conclusion that CUEDC1 was a tumor-suppressive gene appears to conflict with the observations in breast and cervical cancer." (PMID 33099540, 2020). "In early-stage cervical cancer, CUEDC1 was elevated in metastasized tumors compared with non-metastasized tumors." (PMID 33099540, 2020).
non-small cell lung carcinoma (2 papers, 2020 to 2025). A group of at least three distinct histological types of lung cancer, including non-small cell squamous cell carcinoma, adenocarcinoma, and large cell carcinoma. "In this study, we first found that low CUEDC1 expression correlated with lymph node metastasis in non-small cell lung cancer (NSCLC) patients using immunohistochemistry (IHC)." (PMID 33099540, 2020).
adrenocortical carcinoma (1 paper, 2020). "We first found that CUEDC1 was significantly downregulated in adrenocortical carcinoma, bladder urothelial carcinoma, colon adenocarcinoma, kidney renal clear cell carcinoma, prostate adenocarcinoma and thyroid carcinoma tissues." (PMID 33099540, 2020).
Hypertension (1 paper, 2025). The presence of chronic increased pressure in the systemic arterial system. "The CUEDC1 pathway has become an individualized diagnostic and therapeutic target against human hypertension, even in a polygenic context." (PMID 40332416, 2025). "(d) A human Cuedc1 pathway of hypertension pathogenesis is directly implicated, that is, predicated, on its shared origins of mechanisms in mammalian common ancestors in BP control." (PMID 40332416, 2025). "The human CUEDC1 pathway in hypertension pathogenesis has been implicated to originate from mammalian common ancestors and resulted in humans and rodents using the same pathway in blood pressure control." (PMID 40332416, 2025). "From this, we identified a novel pathway of hypertension pathogenesis in vivo controlled by the CUE domain containing 1 protein (Cuedc1)." (PMID 40332416, 2025). "CUEDC1 from the current work and M3R signaling from our previous work are just two separate pathways found in one inbred polygenic model of hypertension." (PMID 40332416, 2025). "(c) A previously unknown adrenal pathway of Cuedc1 has been discovered in pathophysiologically regulating hypertension in a polygenic context." (PMID 40332416, 2025).
lung carcinoma (1 paper, 2020). "Overexpression of CUEDC1 decreased the metastatic potential of lung cancer cells and inhibited the EMT process and inactivated TβRI/Smad signaling pathway." (PMID 33099540, 2020). "We also demonstrated that CUEDC1 knockdown promoted lung cancer progression in vitro and in vivo." (PMID 33099540, 2020). "Furthermore, the Kaplan–Meier plotter was used to assess the impact of CUEDC1 on lung cancer survival (n = 1926)." (PMID 33099540, 2020). "In addition, transwell assays also showed that CUEDC1 knockdown significantly promoted lung cancer cell migration and invasion." (PMID 33099540, 2020). "The GSEA results showed that CUEDC1 was negatively related with the pathway “KEGG Cancer Relapse Tumor Sample Up”, suggesting the suppressive roles of CUEDC1 in lung cancer." (PMID 33099540, 2020).
lymph node metastasis (1 paper, 2020). "Clinicopathological association analyses revealed that low CUEDC1 expression was significantly associated with lymph node metastasis." (PMID 33099540, 2020). "In the present study, we found that low CUEDC1 expression was associated with the presence of lymph node metastasis and survival." (PMID 33099540, 2020). "Elevated CUEDC1 levels may predict favorable survival for the patients with lymph node metastasis." (PMID 33099540, 2020).
osteosarcoma (1 paper, 2022). A usually aggressive malignant bone-forming mesenchymal neoplasm, predominantly affecting adolescents and young adults. "CUEDC1 is correlated with estrogen receptor alpha (ERα), which has been found to confer MTX resistance in osteosarcoma cells." (PMID 35639775, 2022).
preeclampsia (1 paper, 2020). Preeclampsia is a hypertensive disorder of pregnancy that is characterized by new-onset hypertension with proteinuria presenting after 20 weeks of gestation, and depending on mild or severe forms may initially present with severe headache, visual disturbances, and hyperreflexia. "To date, little is known regarding CUEDC1, although CUEDC1 was found to be remarkably lower in a group with preeclampsia compared with the normal pregnancy group." (PMID 33099540, 2020).
tumor (3 papers, 2020 to 2025). "Relative to those implanted with the control cells, the mice implanted with CUEDC1-knockdown cells showed significantly increased tumor volume." (PMID 33099540, 2020). "In summary, the present study showed a working model for how CUEDC1 inhibits NSCLC tumor growth and metastasis." (PMID 33099540, 2020). "On the basis of bioluminescence imaging, we found that CUEDC1 knockdown promoted tumor growth compared with Ctrl at 7, 14, 21 days after the implantation." (PMID 33099540, 2020). "Western blotting results showed that CUEDC1 expression was significantly lower in the tumor tissues than in the adjacent normal lung tissues." (PMID 33099540, 2020). "To further investigate the tumor-suppressive role of CUEDC1 in vivo, we established a xenograft tumor model by subcutaneously injecting shCUEDC1 and Ctrl into nude mice." (PMID 33099540, 2020). "CUEDC1 was clearly expressed in the cytoplasmic and nuclear compartments of tumor cells (P < 0.001)." (PMID 33099540, 2020). "Moreover, CUEDC1 was also significantly downregulated in NSCLC tumor tissues compared with matched surrounding tissues (P < 0.001)." (PMID 33099540, 2020). "In vivo, CUEDC1-knockdown cells promoted metastasis and tumor growth compared with control cells." (PMID 33099540, 2020). "The results suggested that CUEDC1 might efficiently inhibit tumor metastasis through suppressing EMT by the regulation of the Smurf2/TβRI/Smad signaling pathway." (PMID 33099540, 2020). "Similar to CUEDC1, another CUE domain-containing protein, CUEDC2, also appears to have a dual function, either as a tumor promoter or tumor suppressor." (PMID 33099540, 2020). "Therefore, we performed IHC assays to detect the expression of CUEDC1 and EMT markers in NSCLC tumor tissues." (PMID 33099540, 2020). "In addition, CUEDC1 inhibits proliferation and promotes apoptosis of NSCLC cells, blocking tumor growth." (PMID 33099540, 2020). "Although we discovered that CUEDC1 inhibited Bcl-2, C-myc, CyclinD1 and CDK4 expression and facilitated Bax expression, we did not fully elucidate the detailed mechanism by which CUEDC1 promotes tumor growth." (PMID 33099540, 2020).
cancer (1 paper, 2020). A tumor composed of atypical neoplastic, often pleomorphic cells that invade other tissues. "CUEDC1 mRNA levels were detected using GEPIA in different carcinomas." (PMID 33099540, 2020). "Thus, we reasoned that the function of CUEDC1 may be different in different types of cancers, and the multifunctional roles of CUEDC1 in various cancers would suggest its value as a tissue-specific therapeutic target." (PMID 33099540, 2020). "It is interesting to explore the similar molecular mechanisms how CUEDC1 and CUEDC2 inhibit cancer progression, and these mechanisms are worthy of research in the future." (PMID 33099540, 2020). "The similar molecular mechanism how CUEDC1 and CUEDC2 inhibit cancer progression might be they both could inactivate the canonical IκB kinase (IKK)-dependent NF-κB signaling pathway." (PMID 33099540, 2020).
CUEDC1 also shares sentences with these, for which no sentence is quoted: bladder urothelial carcinoma (1 paper); colon adenocarcinoma (1); Perrault syndrome (1); prostate adenocarcinoma (1); thyroid carcinoma (1).